GLP1R (glucagon like peptide 1 receptor)
Description:
G protein-coupled receptor for glucagon-like peptide 1 (GLP-1). Ligand binding triggers activation of a signaling cascade that leads to the activation of adenylyl cyclase and increased intracellular cAMP levels. Plays a role in regulating insulin secretion in response to GLP-1 (By similarity).
Synonyms: GLP-1-R; GLP-1R; GLP-1
Tractability: Small molecule: a drug acting on it is in phase 2 or 3 trials; a structure with a bound ligand is known; a high-quality ligand is known; it belongs to a druggable protein family. Antibody: UniProt places it where antibodies can reach, with high confidence; its Gene Ontology location is reachable by antibodies, with high confidence; UniProt predicts a signal peptide or a membrane-spanning region. PROTAC: a small molecule that binds it is known. Other modalities: an approved drug acts on it.
Target class: Membrane receptor; Family B G protein-coupled receptor; Glucagon-like peptide receptor; Peptide receptor (family B GPCR); Glucagon-like receptor
Safety:
Unwanted effects reported when the protein is acted on. In parentheses: how it was acted on, where the effect was seen, and who reports it.
less weight gain (source: ClinPGx)
weight gain (source: ClinPGx)
Gene: Protein-coding gene on chromosome 6 (39,048,781 to 39,091,303, forward strand). Ensembl gene ENSG00000112164.
Subcellular location: Cell membrane
Subcellular location (Human Protein Atlas): Nuclear bodies; Plasma membrane; Centrosome; Golgi apparatus
Pathways (Reactome):
Signal Transduction: G alpha (s) signalling events; Glucagon-type ligand receptors
Metabolism: Glucagon-like Peptide-1 (GLP1) regulates insulin secretion
Gene Ontology:
Molecular function: glucagon-like peptide 1 receptor activity; protein binding; glucagon receptor activity; peptide hormone binding; transmembrane signaling receptor activity; G protein-coupled peptide receptor activity; G protein-coupled receptor activity
Biological process: adenylate cyclase-activating G protein-coupled receptor signaling pathway; positive regulation of cytosolic calcium ion concentration; activation of adenylate cyclase activity; positive regulation of blood pressure; cell surface receptor signaling pathway; cellular response to glucagon stimulus; G protein-coupled receptor signaling pathway; learning or memory; regulation of heart contraction; response to psychosocial stress
Cellular component: plasma membrane; membrane
Genetic constraint (gnomAD): Loss-of-function variants: 13 observed, 41.84 expected, observed/expected ratio (o/e) 0.31, 90% interval 0.2 to 0.49. The upper end of that interval is the gene's LOEUF score, 0.49, which puts it in group 2 of 6, group 1 being the genes least tolerant of losing a copy. Missense variants: 343 observed, 447.3 expected, observed/expected ratio (o/e) 0.77, 90% interval 0.7 to 0.84. Synonymous variants: 185 observed, 182.7 expected, observed/expected ratio (o/e) 1.01, 90% interval 0.9 to 1.14.
Homologues: Orthologues: chimpanzee GLP1R (99% identical), macaque GLP1R (98% identical), rabbit GLP1R (92% identical), mouse Glp1r (92% identical), guinea pig GLP1R (92% identical), pig GLP1R (90% identical), rat Glp1r (89% identical), dog GLP1R (88% identical), tropical clawed frog GLP1R (68% identical). Paralogues in human: GCGR (46% identical), GIPR (43% identical), GLP2R (42% identical), SCTR (37% identical), VIPR1 (36% identical), ADCYAP1R1 (33% identical), PTH1R (33% identical), VIPR2 (33% identical), GHRHR (32% identical), PTH2R (30% identical), CALCR (25% identical), CALCRL (25% identical), and 30 more.
Diseases named in the same sentence as GLP1R in open-access papers:
GLP1R is named in the same sentence as 487 diseases in open-access papers, as found by Europe PMC text mining. Sharing a sentence is not in itself a finding about the gene and the disease. The quoted sentences say what the papers report.
type 2 diabetes (1,726 papers, 2008 to 2026). "Glucagon-like peptide-1 receptor agonists (GLP-1 RAs) reduce CV risk in type 2 diabetes, but their role in T1DM is less well-defined." (PMID 42123472, 2026). "Previous studies have revealed that glucagon-like peptide-1 receptor agonist (GLP-1RA) can improve metabolic dysfunction-associated steatotic liver disease (MASLD) in individuals with type 2 diabetes (T2D)." (PMID 41246119, 2025). "Several of the lipid‐associated genic hits like CETP, GCKR, and GLP1R are known to function in lipid metabolism, glucose metabolism, type 2 diabetes, and insulin resistance." (PMID 40665476, 2025). "Semaglutide and tirzepatide, the new generation of glucagon-like peptide-1 receptor agonist used to treat type 2 diabetes and obesity, were recently reported to be associated with increased risk of nonarteritic anterior ischemic optic neuropathy (NAION)." (PMID 40788646, 2025). "Associations were identified between GLP1R variants and body mass index (BMI), blood pressure and type 2 diabetes in all ancestries." (PMID 39838854, 2025). "Glucagon-like peptide-1 receptor agonists (GLP-1RAs) are approved for treating type 2 diabetes and weight loss." (PMID 40471297, 2025). "With the rise in glucagon-like peptide 1 receptor agonist (GLP-1RA) medication usage for Type 2 diabetes mellitus and weight loss, concerns have been raised regarding safety and primary aspiration risk when undergoing anesthesia procedures." (PMID 41001395, 2025). "Semaglutide, a glucagon-like peptide-1 receptor agonist, used for Type 2 diabetes mellitus and more recently for weight loss, often causes gastrointestinal adverse effects such as delayed gastric emptying and abdominal discomfort." (PMID 39734391, 2025). "Glucagon-like peptide-1 receptor agonists (GLP-1 RA) are indicated for the treatment of type 2 diabetes and for weight loss (liraglutide and semaglutide)." (PMID 39844933, 2025). "Semaglutide (Ozempic), a glucagon-like peptide-1 receptor agonist used primarily for the management of type 2 diabetes, has been associated with gastrointestinal side effects, but its potential role in inducing ischemic colitis is not well documented." (PMID 40084311, 2025). "A rapidly increasing proportion of the population in the United States is taking glucagon-like peptide-1 receptor agonists (GLP-1RAs) for type 2 diabetes or weight loss." (PMID 40285503, 2025). "Semaglutide is a glucagon-like peptide-1 receptor agonist (GLP-1RA) used to manage type 2 diabetes and, since 2021, for weight loss in individuals with obesity or weight-related comorbidities." (PMID 41025030, 2025). "Treatment with glucagon-like peptide-1 receptor agonists (GLP-1 RAs) is an established therapy for patients with type 2 diabetes that improves glucose control, induces weight loss, and reduces major adverse cardiovascular events." (PMID 41444417, 2025). "On the other hand, the evidence for a causal relationship between glucagon-like peptide 1 receptor agonists (GLP1RAs) and pancreatitis in people with type 2 diabetes is still weak." (PMID 38779453, 2024). "Glucagon-like peptide-1 receptor agonist use has increased over the last decade for glycemic control in type 2 diabetes mellitus, cardiovascular risk reduction, and weight loss." (PMID 38861153, 2024). "Our study revealed that ER stress and its associated signaling events alter GLP-1R’s signaling, which can be used in type 2 diabetes treatment." (PMID 38376482, 2024). "For example, in a nested case–control analysis of patients with type 2 diabetes receiving drug treatment, the treatment of GLP-1R agonists increased the risk of medullary thyroid cancer and thyroid cancer." (PMID 39858999, 2024). "Several peptide dual agonists of the human glucagon receptor (GCGR) and the glucagon-like peptide-1 receptor (GLP-1R) are in development for the treatment of type 2 diabetes, obesity and their associated complications." (PMID 38755312, 2024).
type 2 diabetes (continued). "Subcutaneous semaglutide, a glucagon-like peptide-1 receptor agonist, is gaining popularity for glycemic control in type 2 diabetes mellitus patients due to its lower risk of hypoglycemia, weight loss benefits, and convenient weekly injection." (PMID 39429379, 2024). "For instance, in patients with type 2 diabetes, the hypotensive effects of sodium glucose cotransporter 2 inhibitors and glucagon-like peptide 1 receptor agonists were significantly associated with a reduction in mortality and cardiorenal events." (PMID 38380006, 2024). "Several evidence demonstrated that glucagon-like peptide 1 receptor agonists (GLP1-RAs) reduce the risk of dementia in type 2 diabetes patients by improving memory, learning, and overcoming cognitive impairment." (PMID 38287296, 2024). "Glucagon-like peptide 1 receptor agonists (GLP1-RA) are indicated for the treatment of type 2 diabetes and more recently for weight loss." (PMID 38663923, 2024). "Is treatment with glucagon-like peptide-1 receptor agonists (GLP-1RA) of patients with type 2 diabetes associated with excess risk of pancreatic cancer?" (PMID 38175642, 2024). "The efficacy of glucagon-like peptide-1 receptor agonists (GLP1-RA) in type 2 diabetes mellitus is well-established with weight loss, improved glycemic control without hypoglycemia, and an improvement in cardiovascular outcomes." (PMID 38962634, 2024). "Semaglutide, an agonist of the glucagon-like peptide-1 receptor, is frequently used in the treatment of diabetes mellitus type 2, although, lately, weight loss has additionally become a reason for its use." (PMID 38371020, 2024). "This is a retrospective national cohort study that aims to assess the risk of developing pancreatic cancer in patients with type 2 diabetes mellitus (T2DM) who are being treated with Glucagon-like Peptide-1 receptor agonists." (PMID 38730578, 2024). "Our study aimed to investigate the influence of glucagon-like peptide 1 receptor agonists (GLP-1RA) on cytokine concentrations associated with the initiation of atherosclerotic plaque formation in a group of patients with type 2 diabetes and dyslipidemia." (PMID 38339133, 2024). "Glucagon-like peptide 1 receptor agonists have proven cardiovascular benefits in trials of people with type 2 diabetes at high cardiovascular risk." (PMID 38470420, 2024). "Colocalization analyses indicate that distinct variants in the GLP1R gene region are associated with body mass index and type 2 diabetes." (PMID 38379245, 2024). "We aimed to assess the association between the use of Glucagon-like peptide-1 receptor agonists and the risk of 12 respiratory diseases in patients with type 2 diabetes, obesity, or overweight." (PMID 37491292, 2023). "Among these, the glucagon-like peptide-1 receptor rs3765467 (G⟶A) mutation was statistically associated with early onset type 2 diabetes." (PMID 38131033, 2023). "GLP1R agonists have been found to reduce EAT thickness more effectively than overall weight loss in patients with type 2 diabetes and obesity." (PMID 37304960, 2023). "Recent pharmacological interventions, such as glucagon-like peptide-1 receptor agonists and sodium-glucose co-transporter-2 inhibitors (SGLT2i), can facilitate clinically relevant weight loss in individuals with type 2 diabetes." (PMID 37686725, 2023). "This study investigated semaglutide, a glucagon-like peptide-1 receptor agonist that induces significant weight loss in patients with obesity and/or type 2 diabetes mellitus and has been associated with improved cardiovascular outcomes." (PMID 38094687, 2023). "The GLP-1R agonists lower epicardial adipose tissue thickness more significantly than overall weight loss in patients with type 2 diabetes and obesity." (PMID 37900360, 2023). "Several data in the literature demonstrate that GLP-1R activation can also positively affect autophagy, whose defects have been shown to play a pathogenic role in both type 1 and type 2 diabetes, and in neurodegenerative diseases." (PMID 37333802, 2023).
type 2 diabetes (continued). "Are sodium-glucose cotransporter-2 inhibitors (SGLT-2i) and glucagon-like peptide-1 receptor agonists (GLP-1RA) associated with reduced cardiovascular risk in patients with type 2 diabetes and concomitant nonalcoholic fatty liver disease (NAFLD)?" (PMID 38153732, 2023). "Heterozygous carriers of the rare missense variant T1491.44M of the GLP-1R have a higher risk of type 2 diabetes as result of lower insulin secretion and impaired insulin sensitivity." (PMID 34801547, 2022). "Glucagon-Like Peptide-1 Receptor Agonists (GLP-1RAs) represent injectable therapies for the treatment of type 2 diabetes and provide significant weight loss, resulting from appetite control, increased satiety, and delayed gastric emptying." (PMID 36430774, 2022). "Recent guidelines recommend glucagon-like peptide 1 receptor agonists early in the disease course for high-risk patients, but only 0.5% of patients in our study with type 2 diabetes were using this therapy." (PMID 35755551, 2022). "More specifically, GLP1R rs10305420 has been associated with response to exenatide in overweight patients with type 2 diabetes and liraglutide in obese women with polycystic ovary syndrome." (PMID 35754710, 2022). "Here, we evaluated the role of the GLP-1R agonist in brains of db/db mice, an established animal model of type 2 diabetes associated with mood disorders." (PMID 36615696, 2022). "This cohort study examines the racial, ethnic, sex, and socioeconomic inequities associated with use of glucagon-like peptide-1 receptor agonists in US patients with type 2 diabetes." (PMID 35977298, 2021). "Two further studies from Spain and China explored the relationship between GLP1R variants and weight loss in type 2 diabetes." (PMID 33594477, 2021). "Glucagon-like peptide-1 receptor agonists (GLP-1 RAs) are novel glucose-lowering treatments for type 2 diabetes with low risk for hypoglycaemia." (PMID 31999317, 2021). "Patients with type 2 diabetes mellitus are at increased risk of developing heart failure and evidence from randomized controlled trials supports that GLP1R (glucagon‐like peptide‐1 receptor) agonists reduce this risk." (PMID 34184541, 2021). "Long-acting GLP-1R agonists, liraglutide, semaglutide and dulaglutide have been marketed for the treatment of type 2 diabetes and have been shown to also provide cardiovascular risk reduction, while liraglutide is approved for the treatment of obesity." (PMID 33341919, 2021). "With the recent evidence that SGLT2 inhibitors and GLP1-R agonists provide cardio-renal protection in high-risk individuals with type 2 diabetes, their use should now be considered as a standard of care." (PMID 32650548, 2020). "We aimed to explore the relationship between GLP-1 receptor (GLP-1R) expression in adipose tissue (AT) and incretin secretion, glucose homeostasis and weight loss, in patients with morbid obesity and type 2 diabetes undergoing bariatric surgery." (PMID 31000783, 2019). "In type 2 diabetic patients from a Han Chinese population, some variations in the GLP-1R gene were associated with a lower risk of developing CAD." (PMID 30271789, 2018). "The Effect of glucagon-like peptide 1 receptor agonists on weight loss in type 2 diabetes: a systematic review and mixed treatment comparison meta-analysis." (PMID 29527102, 2018). "Liraglutide, another drug prescribed for weight loss, is known to improve type 2 diabetes in humans and works through activation of the glucagon-like peptide 1 receptor (GLP-1R) in the brain." (PMID 28105413, 2016). "These combined actions of GLP-1R signaling cause improvements in glycemic control as well as weight loss in type II diabetes (T2DM) patients treated with GLP-1R agonists." (PMID 25852463, 2015).
type 2 diabetes (continued). "Changes in cardiovascular risk markers were examined in patients with type 2 diabetes treated with exenatide twice daily (a glucagon-like peptide-1 receptor agonist) or glimepiride (a sulfonylurea) added to metformin in the EURopean EXenAtide (EUREXA) study." (PMID 26338040, 2015). "Although speculative, these findings imply that individuals with type 2 diabetes receiving GLP-1R and/or NPY2R agonists to treat their underlying diseases could possibly profit from both these effects." (PMID 41094027, 2026). "The question then arises as to whether weight loss and modern treatments for type 2 diabetes, in particular glucagon-like peptide-1 receptor agonists and sodium-glucose cotransporter-2 inhibitors, influence the lithogenic risk." (PMID 42272999, 2026). "Basal insulin with glucagon-like peptide-1 receptor agonist could be preferred over premixed insulin for intensification in type 2 diabetes due to better glycemic control, lower hypoglycemia risk, and favorable effects on body weight." (PMID 41268167, 2025). "Thus, the structural and functional engagement of tirzepatide with GLP1R plays a pivotal role in its therapeutic success in type 2 diabetes and associated comorbidities." (PMID 41226200, 2025). "In this cohort study of 269 064 propensity score–matched adult patients with type 2 diabetes, SGLT2i initiation was associated with a higher prevalence of erythrocytosis compared with dipeptidyl peptidase 4 inhibitors and glucagon-like peptide 1 receptor agonists." (PMID 40549381, 2025). "GLP1R has recently been implicated as a multimodal receptor involved in cardiometabolic disease and is targeted by several US Food and Drug Administration–approved drugs for the treatment of type 2 diabetes and obesity." (PMID 39083597, 2024). "Glucagon-like peptide-1 receptor agonists (GLP-1RAs) are multipurpose agents effective in improving glycemic control in patients with type 2 diabetes while also achieving weight loss and risk reduction of major cardiovascular (CV) events and chronic kidney disease progression." (PMID 39258261, 2024). "Synthetic glucagon-like peptide-1 receptor (GLP-1R) agonists are a popular class of therapy for type 2 diabetes mellitus, which a number of studies have suggested may be a risk factor for glaucoma." (PMID 37362000, 2023). "Functional follow-up and molecular dynamics simulations of lower frequency coding variants in glucagon-like peptide-1 receptor (GLP1R), a type 2 diabetes treatment target, reveal that optimal selection of GLP-1R agonist therapy will benefit from tailored genetic stratification." (PMID 37679419, 2023). "GLP-1 receptor (GLP-1R) agonists are known to reduce the risk of CVD in diabetes mellitus type 2." (PMID 36611900, 2022). "For example, the glucagon-like peptide-1 receptor with 30 DNA variants in BN.SHR20 has been a heavily exploited target of type 2 diabetes and obesity therapies by its agonists, and the peroxisome proliferator-activated receptor beta/delta is crucial for fatty acid metabolism in the muscle." (PMID 36014934, 2022). "Third, this cohort has been active since 2009, and contemporary anti-diabetic medications, such as sodium glucose co-transporters 2 inhibitors and glucagon-like peptide-1 receptor agonists, which can reduce mortality risk in patients with type 2 diabetes, were seldom prescribed." (PMID 34207578, 2021). "Further, a clinical study has demonstrated that the combination of GLP-1R agonist and sodium–glucose cotransporter 2 (SGLT2) inhibitors significantly reduces the risk of all cause-mortality and improves renal function, compared to GLP-1R agonist alone in type 2 diabetic patients." (PMID 32384887, 2020). "Of interest, several other known genes coding for satiety-related receptors are highly enriched in the nodose, including the glucagon-like peptide 1 receptor (Glp1r), which also suppresses appetite and has been targeted using synthetic analogs for type II diabetes and weight loss." (PMID 33424545, 2020).